SLC7A11 (solute carrier family 7 member 11)
Diseases named in the same sentence as SLC7A11 in open-access papers (continued):
Sharing a sentence is not in itself a finding about the gene and the disease.
Cerebral ischemia (21 papers, 2021 to 2026). Restriction of arterial blood supply to the brain associated with insufficient oxygenation to support the metabolic requirements of the tissue. "We identified the FoxO3a activator trifluoperazine (TFP), a FDA-approved antipsychotic agent that reduced ferroptosis-associated brain ischemia/reperfusion (CIR) injury in rats through AMPK/FoxO3a/HIF-1α/SLC7A11 signaling and mitochondria-dependent mechanisms." (PMID 37267686, 2023). "Reportedly, rhein is able to inhibit ferroptosis through the NRF2/SLC7A11/GPX4 signaling pathway, attenuate the damage caused by cerebral ischemia/reperfusion, and induce dose-dependent neuroprotective effects." (PMID 40070574, 2025). "Kaempferol has been shown to protect cerebral ischemia-reperfusion injured cells by inhibiting apoptosis and inhibit iron death by activating the Nrf2/SLC7A11/GPX4 signaling pathway." (PMID 38257230, 2024). "HIF-1α promotes cystine-glutamate antiporter (SLC7A11/xCT) expression which contributes to cerebral ischemia-reperfusion (CIR)-mediated glutamate release and excitotoxicity." (PMID 37267686, 2023). "NRF2 activation orchestrates a coordinated defense against cerebral ischemia by transcriptionally repressing ferroptosis through the GPX4/SLC7A11 axis and iron metabolism regulation, while concurrently mitigating oxidative stress, neuroinflammation, and apoptosis." (PMID 41306421, 2025). "Taken together, these findings demonstrated that the Arip1 deficiency attenuated neuronal ferroptosis after cerebral ischemia by increasing endogenous Act A levels, thereby modulating the Act A/SMAD3 and p38 MAPK signaling pathways, ultimately influencing the SLC7A11/GPX4 pathway." (PMID 40965963, 2025). "Therefore, the activation of Nrf2 would increase the expression of SLC7A11 and make differences in resisting oxidative stress and ferroptosis during cerebral ischemia through the signaling pathway jointly participated by SLC7A11/GPX4." (PMID 38393376, 2024). "We speculate that Dl-3-n-butylphthalide has a neuroprotective effect on focal cerebral ischemia/reperfusion, which may be mediated through ferroptosis-dependent SLC7A11/GSH/GPX4 signal pathway and PDGFRβ/PI3/Akt signal pathway." (PMID 36909944, 2023). "Expression of SLC7A11, a cystine/glutamate transporter is significantly increased in malignant glioma and during brain ischemia contributing to increased extracellular glutamate levels resulting in overstimulation of NMDA receptors, seizures and neuronal death." (PMID 36890518, 2023). "Data show that HIF-1α up-regulates SLC7A11 and induces damage by binding to its promoter, while SLC7A11 gene knockout in mice inhibits brain injury induced by cerebral ischemia/reperfusion (CI/R) or oxygen-glucose deprivation/reoxygenation (OGD/R) in vivo and in vitro." (PMID 35481263, 2022). "In this study, we built a model of brain ischemia–reperfusion to observe whether the SLC7A11/GSH/GPX4 and PDGFRβ/PIK/Akt signal pathways were involved in the process; most importantly, we evaluated whether these two pathways could be potential valid targets of DL-NBP treatment." (PMID 36909944, 2023). "Western blot analysis revealed that cerebral ischemia marginally induced the expression of NRF2 and significantly decreased the expression of SLC7A11, GPX4, and FTL (P < 0.05 vs. sham)." (PMID 40474971, 2025). "Research has indicated that electroacupuncture treatment can effectively inhibit ferroptosis by activating Nrf2, increasing protein expression of solute carrier family 7 member 11 (xCT) and GPX4, thereby reducing cerebral ischemia/reperfusion injury." (PMID 41210484, 2025). "For example, baicalein suppresses ferroptosis to decrease cerebral ischemia–reperfusion injury by downregulating the ferroptosis-inducing ACSL4 gene and upregulating ferroptosis-inhibiting genes (GPX4 and SLC7A11) in brain tissues." (PMID 38892270, 2024).
Cerebral ischemia (continued). "Berberine suppresses cerebral ischemia–reperfusion-injury-induced ferroptosis by downregulating ACSL4 and upregulating SLC7A11 expression." (PMID 38892270, 2024).
renal carcinoma (21 papers, 2019 to 2025). A carcinoma arising from the epithelium of the renal parenchyma or the renal pelvis. "Survival analysis was performed on the whole renal cancer samples in TCGA, and high expression of SLC7A11, HMOX1 and MT1G all presented some prognostic risk." (PMID 35360452, 2021). "The survival analysis screening resulted in three DEGs associated with renal cancer prognosis, namely SLC7A11, HMOX1, and MT1G." (PMID 35360452, 2021). "We found that SLC7A11 increased its risk of poor prognosis in four renal cancers." (PMID 35360452, 2021). "During glucose deprivation, renal cancer cells with increased SLC7A11 gene expression depleted NADPH within an hour, resulting in an increase in NADP+/NADPH levels." (PMID 40539058, 2025). "This indicates that SLC7A11 is one of the therapeutic targets for preventing the progression of renal cancer to metastatic renal cancer." (PMID 39021564, 2024). "Under glucose starvation conditions, high expression of SLC7A11 in renal cancer cells accelerates the depletion of nicotinamide adenine dinucleotide phosphate in the cytoplasm." (PMID 38358909, 2024). "Three genes (SLC7A11, HMOX1, and MT1G) were identified as differentially expressed genes (DEGs) associated with renal cancer prognosis using survival analysis screening." (PMID 38609844, 2024). "Another study has revealed that SLC7A11 promotes the migration and invasion of renal cancer cells by enhancing GPX4 export." (PMID 37488128, 2023). "One approach is to target SLC7A11-overexpressing renal cancer cells and inhibit the glucose transport pathway to induce disulfidptosis and suppress tumor growth." (PMID 37946181, 2023). "When renal cancer cells are exposed to a glucose-deprived environment, SLC7A11-induced disulfidptosis occurs, leading to cell death." (PMID 37946181, 2023). "Studies have shown that the expression level of SLC7A11 in tumor tissues of renal cancer patients is significantly elevated, which is closely associated with tumor growth and progression." (PMID 37946181, 2023). "Polycomb repressive complex 1 is an E3 ligase responsible for ubiquitinating histone 2A and downregulating SLC7A11 expression by increasing ubiquitination of histone 2A on the SLC7A11 promoter in human renal cancer cells." (PMID 36147464, 2022). "Our study extends on this basis that SLC7A11 has favorable prognostic ability in other types of renal cancer as well." (PMID 35360452, 2021). "The overexpression of SLC7A11 markedly increased the S phase population of renal cancer cells but blocked the G0/G1 phase cells." (PMID 34761566, 2021). "SLC7A11 was significantly upregulated in renal cancer cells (786‐O and A498) compared to that in normal renal tubular epithelial cells (HK‐2)." (PMID 34761566, 2021). "SLC7A11 is markedly upregulated in multiple cell subtypes of renal cancer and is an unfavorable prognostic factor for RCC." (PMID 34761566, 2021). "Collectively, SLC7A11 upregulation was not only confirmed in multiple datasets, but also in multiple pathological subtypes of renal carcinoma." (PMID 34761566, 2021). "We provide evidence that iron-loaded Lcn-2 not only induces the ROS-Nfr2 axis, but also fosters ISR-dependent expression of SLC7A11 to attenuate erastin-induced ferroptosis in renal cancer." (PMID 34069743, 2021). "The knockdown of SLC7A11 in UMRC6 cells (a BAP1-deficient renal cancer cell line) marginally affects cancer cell proliferation, suggesting that the BAP1-mediated tumor suppression through regulating SLC7A11." (PMID 32103754, 2020). "It has been shown that the glutamate/cystine antiporter SLC7A11 can enhance the glucose dependence of renal cancer cell lines and mesothelioma cell lines by exporting glutamate, and tryptophan metabolism confer enhanced proliferation and metastasis of cancer cells by regulating immune cell function." (PMID 36230834, 2022). "Moreover, overexpression of SLC7A11 was enhanced, whereas silencing SLC7A11 retarded the migratory capacity of renal cancer cells." (PMID 34761566, 2021).
renal carcinoma (continued). "Finally, the biofunctions of SLC7A11 in renal cancer cells and ferroptosis were ascertained by MTT, wound healing, transwell, and western blot assays." (PMID 34761566, 2021). "Finally, SLC7A11 promoted the proliferation, migration, and invasion of renal cancer cells by enhancing GPX4 output, which in turn inhibits ferroptosis." (PMID 34761566, 2021). "More importantly, we confirmed that SLC7A11 could promote the proliferation, migration, and invasion of renal cancer cells by enhancing GPX4 output, which in turn inhibits ferroptosis." (PMID 34761566, 2021). "Herein, for the first time, we confirmed that SLC7A11 could promote the proliferative, migratory, and invasive abilities of renal cancer cells." (PMID 34761566, 2021). "SLC7A11 and HMOX1 were found to be upregulated in renal cancer tissues, while MT1G was downregulated." (PMID 38609844, 2024). "Similar mechanisms were also observed, for lncRNA ADAMTS9-AS1 / miR-5887 /SLC7A11 axis in epithelial ovarian cancer, and lncRNA SLC16A1-AS1 / miR-143-3p/SLC7A11 axis in renal cancer." (PMID 37127605, 2023). "To further clarify the biofunctions of SLC7A11 and GPX4 in renal carcinoma cells, we will perform a series of experiments in vitro in the near future." (PMID 37807410, 2023). "In renal cancer, silencing of SLC16A1-AS1 reduced the expression of SLC7A11 and significantly decreased the GSH/glutathione disulfide (GSSG) ratio in cells." (PMID 37488128, 2023). "Specifically, SLC7A11 and HMOX1 were upregulated in renal cancer tissues, while MT1G was downregulated." (PMID 35360452, 2021). "In summary, we systematically addressed the prognostic ability of SLC7A11, HMOX1, and MT1G in overall renal cancer and different renal cancer subtypes in this study." (PMID 35360452, 2021).
endometrial cancer (20 papers, 2019 to 2025). Primary or metastatic malignant neoplasm involving the endometrium (mucous membrane that lines the endometrial cavity). "Therefore, as salinomycin caused the silencing of SLC7A11 in an endometrial cancer culture, the drug may induce tumor cell death through ferroptosis." (PMID 35625926, 2022). "SLC7A11 is highly expressed in various cancers, including endometrial carcinoma, where its expression correlates with poor patient prognosis." (PMID 41313521, 2025). "The suppression of SLC7A11 gene expression and disruption of glutathione metabolism through NaBu therapy induce ferroptosis in endometrial cancer cells." (PMID 39337406, 2024). "It has been reported that quinone mediates the accumulation of free iron in endometrial cancer cells by regulating heme oxygenase, transferrin and SLC7A11, inducing ferroptosis (Zhang Y.-Y." (PMID 35775079, 2022). "The high expressions of CDKN1A, SLC7A11, and SAT1 were found to be linked to the low stage, grade of pTNM, and longer survival time in endometrial cancer." (PMID 35847989, 2022). "This suggests that the signaling pathway involving NaBu, RBM3, and SLC7A11 could be a potential therapeutic target for the detection and treatment of endometrial cancer." (PMID 39337406, 2024). "A study reported that high expression of ferroptosis regulatory genes CDKN1A, SLC7A11, SAT1, and low expression of ATP5MC3 can prolong the disease‐free survival time of patients with endometrial cancer." (PMID 40821694, 2025). "For example, in endometrial cancer, NSUN2 increases m5C modifications on SLC7A11 mRNA, enhancing its stability and expression, reducing lipid peroxidation, and inhibiting ferroptosis." (PMID 41463199, 2025). "In the case of Ishikawa endometrial cancer cultures exposed to cisplatin, it appears that in the case of MAP3K8 and SLC7A11, the miRNAs regulating their expression act as expression suppressors at the PTGS level." (PMID 35625926, 2022). "In this study, after treatment of AF, the expressions of SLC7A11, GPX4, and FTH1 were upregulated, and the expression of ACSL4 was downregulated, indicating that AF induced the ferroptosis of endometrial carcinoma KLE cells." (PMID 35635082, 2022). "For example, in an endometrial carcinoma cohort (TCGA-UCEC), a higher percentage of cytotoxic T lymphocytes (CTLs) predicted a longer overall survival only in patients with lower SLC7A11 expression, which parallels the results of increased anticancer immunity with increased ferroptosis sensitivity." (PMID 32778143, 2020). "As an important component of cystine transport protein Xc− (system Xc−), SLC7A11 has been found to inhibit ferroptosis by promoting cystine transport, increasing the intracellular cysteine level and GSH level, and also SLC7A11 has been considered to be a poor prognosis factor for endometrial cancer." (PMID 35847989, 2022).
thyroid cancer (19 papers, 2018 to 2025). "Studies have demonstrated that the elevated expression of GPX4, a core ferroptosis regulator, is associated with high-grade thyroid cancer, and another key regulator, SLC7A11, is linked to poor prognosis." (PMID 40299520, 2025). "Obesity-associated protein (FTO) prevents thyroid cancer progression by SLC7A11 m6A methylation in a ferroptosis-dependent manner." (PMID 38166898, 2024). "The overexpression of SLC7A5 and SLC7A11 may be partly attributed to macrophages, and tumor-associated macrophages are activated and present in thyroid cancer microenvironment." (PMID 30558624, 2018). "While iron overload and lipid peroxidation are common features of ferroptosis across malignancies, the specific involvement of thyroid-specific molecules like GPX4 and SLC7A11 in regulating ferroptosis pathways in thyroid cancer is more pronounced." (PMID 39917169, 2025). "Recent investigations have identified the circular RNA Circ_0067934 as a significant contributor to the ferroptosis process in thyroid cancer cells, where it modulates the miR-545-3p/SLC7A11 signaling pathway." (PMID 39917169, 2025). "SLC7A11/xCT, a major transporter of Cys, is reported to be highly expressed in many tumor cells and correlates with poor survival in prostate, breast, and thyroid cancer patients." (PMID 40723225, 2025). "Overexpression of an miR-545-3p inhibitor or SLC7A11 rescued the inhibitory effect of silencing circ_0067934 on thyroid cancer cells and resulted in a decrease in the levels of ferroptosis-associated markers, such as Fe2+, iron, and ROS." (PMID 37332354, 2023). "circ_0067934 competitively binding to miR-545-3p upregulates SLC7A11 to inhibit ferroptosis, promotes thyroid cancer development and advances thyroid cancer treatment." (PMID 37152286, 2023). "Circ_0067934 reportedly upregulates the expression of SLC7A11 and thus promotes the progression of thyroid cancer and inhibits ferroptosis in thyroid cancer cells by adsorbing miR-545-3p." (PMID 37332354, 2023). "Circ0067934 upregulates SLC7A1 expression via the miR-545-3p/SLC7A11 axis, which inhibits thyroid cancer cell ferroptosis and promotes thyroid cancer growth and metastasis." (PMID 37168995, 2023). "Together these data imply that circ_0067934 regulates cell growth and ferroptosis of thyroid cancer cells by miR-545-3p/SLC7A11 axis." (PMID 34290668, 2021). "In this study, we identified that miR-545-3p targets and repressed SLC7A11 expression in thyroid cancer cells." (PMID 34290668, 2021). "In the present study, we identified a novel function of circ_0067934 in inhibiting ferroptosis and tumor growth of thyroid cancer by regulating miR-545-3p/SLC7A11." (PMID 34290668, 2021). "Circ_0067934 upregulated the expression of the ferroptosis-negative regulator SLC7A11 by sponging and inhibiting miR-545-3p in thyroid cancer cells." (PMID 34290668, 2021). "The correlation and effect of miR-545-3p and SLC7A11 in the modulation of tumorigenesis and malignant progression of thyroid cancer cells should be explored in more investigations." (PMID 34290668, 2021). "Meanwhile, we identified that circ_0067934 inhibited ferroptosis of thyroid cancer cells and miR-545-3p potentially targeted ferroptosis-regulator SLC7A11 in a bioinformatics analysis (ENCORI online database)." (PMID 34290668, 2021). "The overexpression of SLC7A11 or the inhibitor of miR-545-3p reversed circ_0067934 silencing-regulated thyroid cancer cell proliferation." (PMID 34290668, 2021). "Additionally, the findings corroborate the expression and functional significance of SLC7A11 in thyroid carcinoma, underscoring its pivotal role in the ferroptosis process." (PMID 39917169, 2025). "Similarly, circ_0067934 suppresses ferroptosis and improves the cell viability of thyroid cancer cells by sponging miR-545-3p and upregulating SLC7A11, indicating that miR-545-3p functions as ferroptosis-inducing miRNA of thyroid cancer cells." (PMID 38892270, 2024).
thyroid cancer (continued). "MiR-545-3p/SLC7A11 axis may just one of the downstream mechanisms of Circ_0067934-regulated thyroid cancer development and other mechanisms deserve to investigate in future studies." (PMID 34290668, 2021). "Furthermore, it has been found that up-regulation of SLC7A11 is correlated with poor prognosis of thyroid cancer." (PMID 34290668, 2021). "The overexpression of SLC7A11 could attenuate miR-545-3p-induced ferroptosis of thyroid cancer cells." (PMID 34290668, 2021). "In addition, the levels of Fe2+, iron, and ROS were enhanced by miR-545-3p mimic, while SLC7A11 overexpression reversed this effect in FTC133 and TPC-1 cells, suggesting that miR-545-3p contributes to ferroptosis of thyroid cancer cells by targeting SLC7A11." (PMID 34290668, 2021). "Therefore, we concluded that Circ_0067934 attenuated ferroptosis of thyroid cancer cells by miR-545-3p/SLC7A11 signaling." (PMID 34290668, 2021). "Moreover, SLC7A11 overexpression in thyroid cancer tissues suggests its inhibition could offer therapeutic benefits." (PMID 40458733, 2025). "We found that Circ_0067934 up-regulated SLC7A11 by down-regulating miR-545-3p and miR-545-3p inhibitor and SLC7A11 overexpression could reverse the cell proliferation regulated by Circ_0067934 depletion in thyroid cancer cells." (PMID 34290668, 2021). "Collectively, these findings highlight the pivotal role of SLC7A11 in the cytotoxic effects of 131I and SAS on thyroid cancer cells." (PMID 40458733, 2025). "ALKBH5, another RNA m6A demethylase, also functions as a tumor suppressor in thyroid cancer cells by decreasing the expression of GPX4 and SLC7A11 to induce ferroptosis." (PMID 40819127, 2025). "This is also the case for thyroid cancers; several amino acid transporters such as SLC7A5 (LAT1), SLC1A5 (ASCT2) and SLC7A11 (xCT) are overexpressed in thyroid cancer tissues, with some of them correlating with patients’ poor prognosis." (PMID 36557253, 2022). "The over-expression of FTO-mediated m6A demethylation inhibits the expression of SLC7A11, thus facilitating ferroptosis in PTC and suppressing the growth of thyroid cancer." (PMID 35721711, 2022). "The miR-545-3p mimic reduced SLC7A11 mRNA and protein levels in FTC133 and TPC-1 cells, suggesting that miR-545-3p targets SLC7A11 in thyroid cancer cells." (PMID 34290668, 2021). "Integrating the dual roles of SLC7A11 in ferroptosis regulation and thyroid cancer progression, we hypothesize that combining SAS with 131I may synergistically enhance treatment efficacy through concerted SLC7A11 inhibition." (PMID 40458733, 2025). "Circ_0067934 functions as a “sponge” for miR-545-3p, inhibiting its activity in thyroid cancer cells and thereby upregulating the ferroptosis-negative regulator SLC7A11, which in turn mitigates ferroptosis in these cells." (PMID 40819127, 2025). "In addition, the levels of Fe2+, iron, and ROS were enhanced by circ_0067934 knockdown, while SLC7A11 overexpression reversed this effect in FTC133 and TPC-1 cells, indicating that circ_0067934 represses ferroptosis of thyroid cancer cells by inducing SLC7A11." (PMID 34290668, 2021).